MIR142 (microRNA 142)
Synonyms: hsa-mir-142; MIRN142; mir-142
Gene: MicroRNA gene on chromosome 17 (58,331,232 to 58,331,318, reverse strand). Ensembl gene ENSG00000284353.
Pathways (Reactome):
Signal Transduction: MTOR signalling
Gene Ontology:
Biological process: miRNA-mediated post-transcriptional gene silencing
Cellular component: RISC complex
Homologues: Orthologues: chimpanzee ptr-mir-142 (100% identical), dog MIR142 (100% identical), macaque MIR142 (100% identical), pig MIR142 (100% identical), rabbit MIR142 (100% identical), rat Mir142 (100% identical), tropical clawed frog xtr-mir-142-1 (90% identical), zebrafish mir142a (87% identical), zebrafish mir142b (87% identical), guinea pig MIR142 (74% identical), mouse Mir142 (74% identical).
Diseases named in the same sentence as MIR142 in open-access papers:
MIR142 is named in the same sentence as 14 diseases in open-access papers, as found by Europe PMC text mining. Sharing a sentence is not in itself a finding about the gene and the disease. The quoted sentences say what the papers report.
chronic lymphocytic leukemia (2 papers, 2022 to 2025). "These genes may include MIR142, for which somatic mutations have been identified in various blood cancers, or MIR15A and MIR16-1, which are commonly deleted and/or mutated in chronic lymphocytic leukemia." (PMID 40867048, 2025).
leukemia (2 papers, 2020 to 2021). A malignant (clonal) hematologic disorder, involving hematopoietic stem cells and characterized by the presence of primitive or atypical myeloid or lymphoid cells in the bone marrow and the blood. "Therefore mutations in NPM1 and Mir142 may provide a convergent role in IDH-mutant leukemias, namely to activate HOX gene expression." (PMID 33173219, 2020). "Combining the loss-of-function due to miRNA Mir142 with IDH2R140Q mutation in vivo, only recipients of double mutant cells developed fatal leukemia, since HOXA cluster genes in myeloid progenitors were alleviated by Mir142 loss-of-function." (PMID 33898313, 2021). "Furthermore, GFP+ leukemia cells infiltrated into the spleen and liver, and double mutant (Mir142−/− + IDH2R140Q) recipients exhibited more severe splenomegaly compared to both the single mutant (WT + IDH2R140Q) recipients and the Mir142 knockout alone." (PMID 33173219, 2020).
hepatocellular carcinoma (1 paper, 2020). A malignant tumor that arises from hepatocytes. "Hypermethylation-induced silencing of MIR142 promotes the progression of hepatocellular carcinoma via failing to suppress TGF-β expression." (PMID 32528944, 2020).
T cell lymphoma (1 paper, 2020). "Recent relevant studies have also confirmed that DNA methylation in MIR142 promoter can be recognized as a novel biomarker for T cell lymphoma." (PMID 32528944, 2020).
infection (1 paper, 2021). The state of being infected such as from the introduction of a foreign agent such as serum, vaccine, antigenic substance or organism. "However, Mir142–/– ILC2s were inhibited from effector cytokine production at both baseline and in response to infection." (PMID 34021046, 2021). "However, proliferative responses of Mir142–/– ILC2s were significantly impaired following infection compared with WT ILC2s from infected mice, which significantly upregulated Ki-67 compared with ILC2s from infection naive WT lungs." (PMID 34021046, 2021). "However, despite the elevated expression of these receptors by Mir142–/– ILC2s from naive mice, ST2 expression was further enhanced by Mir142–/– ILC2s in response to infection as was Klrg1." (PMID 34021046, 2021).
tumor (1 paper, 2020). "In accordance with the related results, MIR142 was predicted as one of the most potential genes for tumor classification." (PMID 32528944, 2020).
MIR142 also shares sentences with these, for which no sentence is quoted: acute myeloid leukemia (1 paper); Autoimmunity (1); blood cancers (1); cancer (1); diffuse large B-cell lymphoma (1); helminth infection (1); myeloid leukemia (1); Splenomegaly (1).